CCND2 (cyclin D2)
Diseases named in the same sentence as CCND2 in open-access papers (continued):
Sharing a sentence is not in itself a finding about the gene and the disease.
tumor (continued). "In a study on nude mice, the Western blot analysis revealed that the expression of CCND2 in hsa_circ_0000231-overexpressing tumor tissues was much higher than that in the mock group." (PMID 35033075, 2022). "After transcription, SURC was transferred to the cytoplasm and inhibits miR–185-5p expression via binding to miR–185-5p, which results in CCND2 expression, cell proliferation, and tumor growth." (PMID 35617032, 2022). "MSCs can block Wnt signaling by regulating the Dickkopf-related protein 1 (DKK1) secreted by tumor cells, downregulating c-Myc and Cyclin D2 and upregulating the expression of P21CIP1 and P27KIP1, resulting to tumor cell suppression." (PMID 36225602, 2022). "Immunostaining showed lower protein expression of Wnt7a, Wnt7b, Mmp7 and Ccnd2 in tumor tissues of the PRDX6 knockout group compared to the wild-type group." (PMID 36209344, 2022). "Immunoblot result suggests CCND2 upregulated in tumor (n = 4) compared to normal ovary tissues (n = 4)." (PMID 35306579, 2022). "We verified that the cell cycle position of MAPK-inhibited tumor cells can be manipulated by downregulating Cyclin D2 or blocking CDK4/6 activity via Palbociclib." (PMID 33821796, 2021). "By analyzing a CLIP‐Seq dataset reported in a previous study, we found that some mRNAs among the top 100 IGF2BP2‐binding mRNAs, such as C‐MYC, AKT3, IGF1R, and CCND2, were closely related to tumor progression." (PMID 34185427, 2021). "For the patient with two CRLM with CCND2 amplifications (29 and 47 additional copies), the primary tumor had 32 additional copies of this gene." (PMID 33325154, 2021). "As reported, miR-26b-5p is a tumor suppressor and modulator in cell cycle regulation that targets different genes, including CCND2, PLOD2, JAG1, MAP3K9 and KPN2." (PMID 34488538, 2021). "The expression of CCND2 fluctuates in normal diploid cells and Rb-positive tumor cells, and its peak is at the late stage of G1." (PMID 32820798, 2021). "GC also shows significantly decreased expression of miR-206, which is a potential tumor suppressor acting via cyclin D2 (CCND2), a protein that plays a key role in controlling the cell cycle." (PMID 33921696, 2021). "Collectively, our results suggested that miR-206 acts as an important tumor suppressor that represses CDDP resistance by affecting the level of CCND2, BAG3, VEGF-A, and other downstream genes of miR-206." (PMID 34746018, 2021). "For example, in BC tumor cells, miR-503, produced and released by endothelial cells, impairs tumor growth by targeting cyclin D2 and D3 (CCND2 and CCND3)." (PMID 34359591, 2021). "The present study demonstrated that AVT inhibits MM cell proliferation in culture and impairs MM tumor growth in vivo, which is consistent with c-Maf/CCND2/ITGB7 activity." (PMID 33627137, 2021). "We assessed the tumor suppressor effect of CCND2 AS1 overexpression in vivo using a mouse xenograft model." (PMID 32607313, 2020). "We also found that the expression of Ki-67, cyclin D2, and cyclin A was markedly reduced in tumor tissues from MACC1-depleted groups than in those from the controls." (PMID 33425885, 2020). "The high sensitivity of the RNAscope technology used in our study can more accurately detect the expression of CCND2 mRNA in tumor tissue in situ." (PMID 32850340, 2020). "Comparative analysis of CCND2 gene expression between paired tumor and normal samples revealed upregulation of CCND2 expression in 26 cases (31.7%)." (PMID 32224897, 2020). "Co-IP study suggests that two tumor-suppressors, CCND2 and IRF5 are part of the immune-complex of FBXL8." (PMID 32784654, 2020). "Mechanistically, cyclin D2, frequently thought to play a critical role in promoting tumor cell proliferation, was upregulated in GATA1 overexpressed cells." (PMID 31093285, 2019). "In line with this, SCCOHT tumor samples expressed variable levels of CCND2, in contrast to HGSCs, which all exhibited low CCND2 expression." (PMID 30718512, 2019).
tumor (continued). "Conversely, the methylation proportion of CCND2 in the sample of Tumor 8 was 0 and this value is compatible with a homogeneous allele population." (PMID 30953488, 2019). "We found that the expression of cell cycle-related tumor suppressor genes, CCND2 and CDKN1A, was increased after CCRT." (PMID 31097034, 2019). "For instance, cyclin D2 (CCND2) expression in our PDX cohort has a −4.771 log2 fold change expression compared to the primary donor tumor (down-XDG), indicating marked downregulation in the PDX." (PMID 31004097, 2019). "The results further revealed reduced FGF9 and CCND2 staining intensities in xenograft tumors in the miR-4317 agomir group compared with the NC group, indicating a decrease in tumor cell proliferation in response to the downregulation of miR-4317." (PMID 30227870, 2018). "The genes in the leading edge of the GSEA included Myc, Ccnd1 and Ccnd2, consistent with the delay in tumor development in mice harboring G3 MB overexpressing WDR11." (PMID 29029386, 2017). "Copy number analysis based on exome sequencing data using VarScan software showed that the genome area hosting ATM, BRCA2 and CCND2 genes had >2-fold intensity changes in all three paired tumor samples compared to matched normal tissue samples." (PMID 28423512, 2017). "The established activities of DYPS, MAL, and TIG1 are consistent with tumor suppression while CCND2, HSPB1 and PITX2 are mainly oncogenic." (PMID 27708246, 2016). "We also measured the expression of Ki67, CCND1 and CCND2 in xenograft tumor tissues using immunohistochemistry." (PMID 27494902, 2016). "In contrast, only 1/23 adjacent non-malignant tissue showed slightly decreased expression of CCND2 compared with RCC tumor tissue (p<0.05)." (PMID 27583477, 2016). "Results showed that Ki67, CCND1 and CCND2 were significantly downregulated in miR-146a-5p-stably-overexpressing tumor tissues." (PMID 27494902, 2016). "We also analyzed the correlation between CCND2 methylation and clinicopathological features such as gender, tumor diameters, pathological stage, nuclear grade and histological classification." (PMID 27583477, 2016). "The aim of our study is to provide novel insight into the mechanism, by which tumor suppressive miRNAs are reduced via c-Myc resulting in up-regulates CCND2, as the potential therapeutic target for ES." (PMID 26393798, 2015). "In this context, miR-503 appears to be an antitumor miRNA secreted by endothelial cells that is able to regulate tumor cell proliferation and invasion via the inhibition of CCND2 and CCND3." (PMID 25860935, 2015). "Treatment of mice with honokiol resulted in a marked decrease in the expressions of cyclin D1 and cyclin D2 and reduced expressions of Cdk4 and Cdk6 in tumor samples obtained from honokiol-treated mice compared to tumor samples from control mice." (PMID 26020804, 2015). "Our data also suggest that CCND2 is one of the crucial factors to enhance tumor proliferation in ES, as other malignant tumors." (PMID 26393798, 2015). "The methylation status of RASSF1A, DAPK1 and CCND2 in tumor-adjacent tissues was significantly different from that in tumors." (PMID 26370119, 2015). "Taken together, these results demonstrate that endothelial-derived miR-503 induces the inhibition of tumor cell proliferation and invasion via inhibition of CCND2 and CCND3." (PMID 25860935, 2015). "While silencing of CCND2 expression by promoter methylation is associated with cancer progression in some cancer types, over-expression of cyclin D2 correlates with progression and poor prognosis in other tumor types." (PMID 24980822, 2014). "In conclusion, we have demonstrated a novel mechanism by which Lin28b over-expression promotes tumour progression via additional Let-7 gene targets such as CCND2, IGF2BP2, and IGF1R." (PMID 23482325, 2012).
tumor (continued). "Double knockout (dKO) studies in our laboratory revealed that p27 and cyclin D2 are important modifiers of the Inha KO phenotype as Inha/Cdkn1b dKOs had accelerated cancer development, whereas Inha/Ccnd2 dKOs had attenuated tumor formation." (PMID 20676395, 2010). "In the current study, the participation of MBDs in the transcriptional repression of the four selected tumour-associated genes CD44, Cyclin D2, GLIPR1 and PTEN was examined." (PMID 20565761, 2010). "This study is one of the first to reveal the histone code and MBD profile at the promoters of CD44, Cyclin D2, GLIPR1 and PTEN in different tumour cells and associated changes after stimulation with methylation inhibitor 5-aza-CdR." (PMID 20565761, 2010). "Patients with presence of BCL2, CCND2, BCL6 and LMO2 mRNA in plasma showed higher expression levels for each gene in tumor tissue, although we only observed a significant association for BCL2 mRNA." (PMID 20016842, 2009). "Methylation of CCND2 has been correlated with poor prognosis, implying that CCND2 has a tumor-suppressor function." (PMID 18485221, 2008). "In 15 cases (26%), two cyclin D proteins were overexpressed in the same tumour, the majority being pairs including cyclin D2." (PMID 16012517, 2005). "We also found that in 15 cases (26%), a single cyclin D protein was overexpressed in a given tumour, predominantly cyclin D2." (PMID 16012517, 2005). "For example, in case 6, cyclin D2 protein was overexpressed in tumour, as compared to the adjacent normal tissue." (PMID 16012517, 2005). "Furthermore, it sponges tumor suppressive miRNAs, such as miR-1, thus enhancing cyclin D2 (CCND-2) and contributing to tumor progression." (PMID 41489907, 2026). "In addition to regulating the cell cycle, CCND2 is also closely related to cell differentiation and tumor transformation." (PMID 40678058, 2025). "The Wnt pathway (CCND2) regulates cell differentiation and development; proper control may prevent tumour progression when WWOX is sufficient." (PMID 41007296, 2025). "Hypermethylation of the CCND2 promoter may reduce CCND2 expression and participate in tumor occurrence and development in UCEC." (PMID 40678058, 2025). "The database collected CCND2 mRNA data from 546 tumor tissues and 35 normal tissues." (PMID 40678058, 2025). "MORC3 deficiency downregulated the E-cadherin (CDH1) tumor suppressive gene and the keratin 14 (KRT14) epithelial differential marker but significantly upregulated the expression of oncogenic JUN, CCND1, CCND2, and CCN1 at the transcriptional level." (PMID 39329063, 2024). "We identified a tumor stem cell cluster (cluster 0) with Axin2, Sox4, Ccnd2, and Clu expression." (PMID 38893159, 2024). "To investigate the involvement of cyclin D2 in tumor development of L1-expressing human CRC cells, we isolated LS 174T cells, stably transfected with L1 in which the levels of endogenous cyclin D2 were suppressed using shRNA constructs compared to cyclin D2 (L1+shcyclin D2, cl1, and cl2)." (PMID 39513917, 2024). "The up-regulation of the Cyclin D2 (CCND2) and the ETS Variant Transcription Factor 1 (ETV1), whose dysregulation may trigger initiation and progression of multiple types of tumours was also highlighted." (PMID 38528259, 2024). "This study shows that the induction of cyclin D2 expression by L1 in CRC cells is a critical step in tumor development and that the inhibition of the various signaling pathways involved in this process could provide therapeutic targets against CRC development." (PMID 39513917, 2024). "Tumor cells showed reduced levels of H3K4me1, H3K4me3, and H3K27ac compared to normal cells; reduced enrichment of these modifications was observed in several genes, including the CCND2 (cyclin D2) locus." (PMID 39199659, 2024). "Mel‐18, a gene promoter regulator, might affect c‐myc, bcl‐2, cyclin D2, and Hox, which induce tumor cell proliferation, metastasis, and angiogenesis." (PMID 36864013, 2023).
tumor (continued). "Molecular characterization of the CAM tumor employing markers such as cyclin D2, ETV4 or WT1 could thus be carried out." (PMID 34685592, 2021). "Furthermore, gene silencing of Ccnd2 inhibits tumor growth in mice, pointing to the significance of this gene for CDS." (PMID 34685592, 2021). "In our study, we showed cyclin D2 expression in the CAM tumor." (PMID 34685592, 2021). "MiR-16-5p is a tumor suppressor for a variety of cancers, and CCND2 can promote tumor progression." (PMID 33993193, 2021). "The results showed that upregulation of circACTN4 could increase the expressions of MYC, CDK4, CCND2 and Ki67 in tumor tissues, whereas circACTN4 silencing reduced the expression levels of these proteins." (PMID 34116677, 2021). "In addition, miR-1297, miR-154, and miR-497 have been reported to target down-regulation of CCND2 to inhibit tumor cell proliferation and migration." (PMID 32820798, 2021). "Up‐regulated CCND1 and CCND2 expression are related to tumor metastasis." (PMID 33473276, 2021). "These chemotherapeutic drugs may respond more strongly to tumor tissues with high CCND2 mRNA expression, making them more effective for patients with such tumors." (PMID 32850340, 2020). "Moreover, we detected eight gene amplifications in six different tumor specimens, including CCND2 (n = 3), FLT3 (n = 3), FGFR1, and MYC." (PMID 33322358, 2020). "In future studies, it might be interesting to analyse the expression of OLIG2 and CCND2 also at the invasive tumor edge and to perform validation of our biomarkers with different techniques such as RNA sequencing." (PMID 31568682, 2020). "Both CCND2 and MMP9 transcripts harbor 3′-UTR recognition sites for miR-204 suggesting that miR-204 may play a tumor suppressor role in RB progression by targeting CCND2 and MMP9." (PMID 32070426, 2020). "Protein levels of Cyclin D2 are also elevated, as would be expected in tumor tissue." (PMID 31541170, 2019). "In this study, we demonstrate that re-expression of RUNX3 in KGN cells promotes cell growth, colony formation, and migration in vitro, as well as tumor formation in mice, which likely involves regulating the expression of cyclin D2 and p27Kip1, two key cell cycle regulators in GCT." (PMID 31311113, 2019). "Finally, miR-193a was shown to have a tumor-suppressor activity by targeting Caprin1, an upstream activator of the G1/S-specific cyclin-D2 (Ccnd2) and the proto-oncogen transcription factor c-Myc." (PMID 31737071, 2019). "The results demonstrated a highly significant increase in PICOT mRNA expression in LUAD compared to LUAD NAT, and a highly significant decrease in CCND2 mRNA expression in LUAD compared to LUAD NAT suggesting that increased PICOT and decreased CCND2 mRNA levels can serve as a tumor marker in LUAD." (PMID 31527584, 2019). "Interestingly, such a mutation correlated with the splicing-dependent inactivation of the PTCH1 tumor-suppressor gene and activation of the GLI2 and CCND2 oncogenes in SHH-MB, supporting the biological relevance of U1 snRNA mutation in this tumor." (PMID 31861467, 2019). "Discrepant mRNA levels of CCND2/3 were observed in normal or tumor tissue in various cancers." (PMID 30950241, 2019). "However, the amplification and extremely high expression of CCND2 (among the highest in > 900 PCGP tumors) suggested that the RB pathway was also compromised in this tumor." (PMID 30262806, 2018). "Some studies demonstrated that miR-154-5p could act as a tumor suppressor gene through targeting CCND2, STAG2, E2F5, HMGA2 and TLR2." (PMID 30266084, 2018).
tumor (continued). "Molecular analysis of the tumor tissues showed that USP22 knockdown reduced the levels of cyclin D2, Akt phosphorylation, vimentin, and Bcl-2, whereas upregulated the expressions of E-cadherin, Bax, and cleaved (cl)-caspase-3, which confirmed in vitro findings." (PMID 27145278, 2016). "The different expression of CCND2 in different type of tumor indicated that CCND2 may function as an oncogene or TSG in a tumor type-dependent manner." (PMID 27583477, 2016). "Moreover, miR-206 is a potential tumor suppressor with G0/G1 cell cycle arrest by targeting the Cyclin D2." (PMID 27192121, 2016). "After ectopic expression of CCND2, we found the ability of tumor growth was inhibited." (PMID 27583477, 2016). "It has been shown that the expression of cyclin D2 (CCND2) could serve as a molecular marker for the more aggressive tumor subtype and a strong predictor for survival time in this group of NPC patients." (PMID 25999660, 2015). "It is also shown that CCND2 is directly regulated by so-called tumor suppressive miRNAs." (PMID 26393798, 2015). "We also explored whether c-Myc would regulate the expression of let-7a, miR-16 and miR-29b and these tumor suppressive miRNAs suppress the expression CCND2." (PMID 26393798, 2015). "Based on the inverse correlation between let-7a/miR-16/miR-29b and c-Myc and CCND2 expression, we hypothezed that down regulation of c-Myc would restore the expression of tumor-suppressive miRNAs, let-7a, miR-16 and miR-29b, subsequently down-regulate CCND2 in ES cell lines." (PMID 26393798, 2015). "In addition, the CMIs of CDKN2B, RASSFIA, DLC1 and CCND2 in the OCSPCs from ascites were significantly higher than those in the OCSPCs from tissues (p = 0.001) or bulk tumor cells (p = 0.038)." (PMID 26597084, 2015). "As we have previously reported, this treatment regimen markedly prolongs survival of tumor-bearing mice and is associated with reduced E2F1 and FASN expression and with diminished proliferation in the tumors, as indicated by reduced levels of cyclin D2." (PMID 22407012, 2012). "In the present study, the promoters of the four above-described tumour-associated genes (CD44, Cyclin D2, GLIPR1 and PTEN) were examined for methylation-dependent gene regulation, the participation of MBDs in gene silencing and the histone modifications associated with the respective promoter areas." (PMID 20565761, 2010). "These facts suggest that CCND2 controls proliferation of UTOS-1 tumor cells." (PMID 19239720, 2009). "In the subset of tumours suited for quantitative PCR analyses, we profiled the mRNA expression of RELA (encoding for RelA/p65) and a number of NF-κB target genes, such as BCL2L1 (Bcl-xL), CCND1 (Cyclin D1), CCND2 (Cyclin D2) and NFKBIA (IκBα)." (PMID 17622249, 2007). "However, our results suggest a 90% significant correlation between cyclin D2 protein overexpression and higher tumour stages." (PMID 16012517, 2005). "As such, and being positively correlated with the metastatic potential of the tumour (this study), cyclin D2 expression may serve as an early marker for colon tumorigenesis and for prediction of clinical prognosis of colon cancer." (PMID 16012517, 2005). "The detection of cyclin D2 mRNA expression in tumours with promoter hypermethylation may be related to the extreme sensitivity of the test, which can theoretically detect as little as 0.1% of methylated cells." (PMID 12771922, 2003). "Additionally, CCND2A (cyclin D2, key regulator of cell growth and replication) amplifications are highly prevalent in G34-mutant tumor tissue, especially those with primitive neuronal/neuroectodermal-like histology; questioning the efficacy of long-term cyclin-dependent kinase (CDK) inhibitor usage." (PMID 40813437, 2025). "However, persistent CM proliferation could lead to tumor growth or the development of arrhythmogenic complications; thus, the goal of the current study was to generate a line of hiPSCs in which CCND2 overexpression could be tightly controlled." (PMID 39201401, 2024).